RNU6-762P (RNA, U6 small nuclear 762, pseudogene)
Gene: Small nuclear RNA gene on chromosome 2 (200,899,020 to 200,899,121, forward strand). Ensembl gene ENSG00000252916.
Homologues: Orthologues: chimpanzee U6 (99% identical), macaque U6 (96% identical), dog U6 (81% identical), mouse Gm22321 (72% identical). Paralogues in human: RNU6-536P (85% identical), RNU6-116P (84% identical), RNU6-1270P (84% identical), RNU6-140P (84% identical), RNU6-24P (84% identical), RNU6-1019P (83% identical), RNU6-1060P (83% identical), RNU6-12P (83% identical), RNU6-13P (83% identical), RNU6-19P (83% identical), RNU6-32P (83% identical), RNU6-33P (83% identical), and 1287 more.